GFAP (glial fibrillary acidic protein)
Diseases named in the same sentence as GFAP in open-access papers (continued):
Sharing a sentence is not in itself a finding about the gene and the disease.
intracerebral hemorrhage (25 papers, 2013 to 2025). A cerebrovascular disorder characterized by bleeding into one or both cerebral hemispheres including the basal ganglia and the cerebral cortex. "Intracerebral hemorrhage, as a result of cerebrovascular disease, is associated with elevated levels of GFAP." (PMID 29255443, 2017). "The concentrations of both UCH-L1 and GFAP were found to be significantly increased in patients with intracerebral hemorrhage compared to those in the control group (p < 0.0001)." (PMID 40649119, 2025). "In intracerebral hemorrhage, however, GFAP is rapidly released from destructed tissue into the blood stream." (PMID 38581002, 2024). "GFAP’s presence in the blood serves as an indicator of intracerebral hemorrhage, allowing for timely and accurate diagnosis." (PMID 39796043, 2024). "An acute intracerebral hemorrhage leads to an immediate mechanical destruction of the astroglia with subsequent release of GFAP into the bloodstream." (PMID 32492963, 2020). "Serum GFAP is a sensitive, specific biomarker of intracerebral hemorrhage in patients with acute stroke symptoms." (PMID 32266274, 2020). "The astroglial protein GFAP is a blood biomarker indicative of intracerebral hemorrhage in patients with acute stroke." (PMID 30304049, 2018). "GFAP is released in case of intracerebral hemorrhage or massive traumatic brain injury (e.g., resulting from shooting) leading to death." (PMID 30304049, 2018). "In order to identify potential “specificity gaps” of a future GFAP test used to diagnose intracerebral hemorrhage, we measured GFAP in the blood of a large and rather unselected collective of patients with neurological diseases." (PMID 23626774, 2013). "The brain-specific astroglial protein GFAP is a blood biomarker candidate indicative of intracerebral hemorrhage in patients with symptoms suspicious of acute stroke." (PMID 23626774, 2013). "A future GFAP blood test applied to identify patients with intracerebral hemorrhage is likely to have a high specificity." (PMID 23626774, 2013). "Recently, the astroglial protein GFAP has been identified as a potential blood biomarker of intracerebral hemorrhage (ICH) in patients with symptoms of acute stroke." (PMID 23626774, 2013). "- GFAP shows high accuracy in differentiating between ischemic stroke and intracerebral hemorrhage." (PMID 41152969, 2025). "The findings indicated that GFAP levels may serve as a valuable adjunctive tool for differentiating between intracerebral hemorrhage and acute ischemic stroke." (PMID 40649119, 2025). "Similarly, for traumatic brain injury (TBI), studies showed that higher GFAP serum concentrations indicated “focal cerebral mass lesions” (i.e. intracerebral hemorrhage)." (PMID 38581002, 2024). "It is possible that rapid astroglial destruction (as in the acute aftermath of severe TBI or an intracerebral hemorrhage) may be required to observe increases in GFAP in blood." (PMID 36153327, 2022). "One study indicated that serum GFAP may function as a reliable biomarker for intracerebral haemorrhage in acute stroke." (PMID 26264492, 2015). "However, GFAP levels may be normal or only slightly elevated in patients with small intracerebral hemorrhages." (PMID 37483444, 2023). "Blood sampling for S100, GFAP, NR2, IL6, and BNP can potentially differentiate intracerebral hemorrhage (ICH) and IS, but their overall discriminatory ability is low." (PMID 39459548, 2024). "Indeed, GFAP could serve as an important blood biomarker for intracerebral hemorrhage." (PMID 38087190, 2023). "- GFAP and LYN are central hubs in intracerebral hemorrhage-related protein networks." (PMID 41152969, 2025).
neuropathy (25 papers, 2014 to 2025). A disorder affecting the nervous system that manifests with pain, tingling, numbness, and/or muscle weakness. "Because the protective effects of MSR1 in nematode models of neurodegenerative pathology are paralleled by similarly positive results in cultured human neuroblastoma cells, GFAP and AD-associated kinases hold promise as novel targets for drug interventions to ameliorate AD-like neuropathies." (PMID 35890250, 2022). "Thus, the increase in neuroglial cells and GFAP expression are thought to be associated with onset and development of neuropathy in the diabetic retina." (PMID 25215304, 2014). "On the other hand, the fact that GFAP protein was overexpressed in the lumbar dorsal horn of mice with paclitaxel-induced neuropathy supports the involvement of astrocytes in allodynia and hyperalgesia observed in those animals." (PMID 37176065, 2023). "The role of spinal glia in neuropathy was first suggested when enhanced levels of glial fibrillary acidic protein (GFAP; an astrocyte marker) and integrin αM (OX-42; a microglia marker) were found in neuropathic pain models." (PMID 37513935, 2023). "Prior to inducing neuropathy, GFAP-DOR-KO mice showed overall elevated nociceptive mechanical thresholds as compared to their control DOR-flox littermates." (PMID 34602984, 2021). "According to several studies of neuropathic pain, including oxaliplatin-induced neuropathy, upregulated GFAP is manifested as the activation of astrocytes." (PMID 34445514, 2021). "Increased circulating GFAP was observed in inflammatory and chemotherapy-induced neuropathies." (PMID 40192786, 2025). "This suggests that lower GFAP may indicate small nerve fiber damage, positioning GFAP as a potential biomarker for small fiber neuropathy." (PMID 41302503, 2025). "Unlike NfL, GFAP has not been widely evaluated in diabetic neuropathies, reducing the likelihood of linking this biomarker to neuropathy caused by vascular injury." (PMID 39156689, 2024). "Similarly, Zhang and co-workers found that minocycline inhibited GFAP upregulation in spinal astrocytes in a rat model of paclitaxel-induced neuropathy." (PMID 34446062, 2021). "Recapitulation of the SOD1G93A:GFAP-luciferase neuropathy with SOD1:GFAP-luciferase mice that have undergone precise mechanical denervation using the cut-and-crush method of sciatic nerve injury provided some credible evidence for this hypothesis." (PMID 25147799, 2014). "Changes in the level of this chemokine in the spinal cord were observed between the 2nd and 28th days of neuropathy induced by sciatic nerve injury, which coincided with changes in IBA-1, GFAP and MPO levels." (PMID 36611891, 2022). "Despite this, we showed that the expression especially of NGF, NGFR, NTRK1, GFRA1, GFAP, and GDNF was upregulated in patients with severe neuropathy as compared to healthy subjects and diabetic patients with subclinical neuropathy." (PMID 30648113, 2018). "The 2-fold increase in spinal GFAP with no apparent change in the level of CD11b protein points to a role of astrocytes in paclitaxel-induced neuropathy." (PMID 37176065, 2023). "Furthermore, the immunostaining results revealed that in the T2DM neuropathy rats, the expression of FIB, GFAP, and IBA1 was upregulated, and the expression of CD31 and Bcl-2 was downregulated." (PMID 37165590, 2023). "GFAP has been identified as a protein with increased abundance in the sciatic nerves of the CMT4C mouse model and increases of this protein has already been described in the aetiology of other neuropathies and is important for nerve regeneration." (PMID 30562927, 2018). "Our results support the hypothesis that spinal microglial P2X4R contribute to neuropathy development, since we have observed spinal upregulation of P2X4R levels at every time point in parallel with activation of IBA-1-positive and GFAP-positive cells." (PMID 28275350, 2017).
neuropathy (continued). "Interestingly, simvastatin had been found to prevent overexpression of GFAP in the partial sciatic nerve injury mouse model of neuropathy, although a reversing (curative) effect was not addressed in that study." (PMID 37176065, 2023). "Analysis of GFAP immunoreactivity reveal elevated spinal astrocyte responses in Sac and PAE rats with minor CCI given a vehicle (Veh) injection compared to their corresponding sham groups, with the greatest increase of astrocyte activation observed from PAE rats with neuropathy induced by minor CCI." (PMID 30961664, 2019). "However, it is possible that GFAP levels do not remain high for too long, as it happens in a neuropathy, since MA is still a model triggered by an inflammatory insult." (PMID 25247596, 2014). "Increases in astrocytic activation (GFAP) with no corresponding changes in microglial activation (OX42, Iba1, and phosphorylated p38) were also recently observed with the same paclitaxel-induced neuropathy dosing protocol used here." (PMID 24742127, 2014).
cardiac arrest (23 papers, 2012 to 2025). Cessation of breathing and/or cardiac function. "GFAP is an astrocytic marker that is produced as part of a neuroprotective mechanism and has been reported to be associated with prognosis after head trauma, intracerebral hemorrhage, ischemic stroke, and cardiac arrest." (PMID 36927495, 2023). "The release pattern of GFAP into the blood after cardiac arrest included an early and continuous rise in patients with poor neurological outcomes, likely explaining the predictive value at 12 h." (PMID 38594704, 2024). "GFAP and tau are promising novel biomarkers for predicting neurological outcome after cardiac arrest, with the highest predictive performance at 48 h after OHCA." (PMID 38594704, 2024). "GFAP is elevated in serum or plasma after cardiac arrest, intracerebral haemorrhage, head trauma, and ischemic stroke." (PMID 38594704, 2024). "We set out to develop an assay detecting the neo-epitope generated by caspase-6 cleavage of GFAP (GFAP-C6), and to assess the ability of GFAP-C6 to reflect pathological processes in patients suffering a cardiac arrest and subsequent global cerebral ischemia." (PMID 31693684, 2019). "A partial recovery in immunoreactivity of GFAP+ astrocytes was observed on Day 10 after cardiac arrest and resuscitation, albeit the level of GFAP+ immunoreactivity was still higher than that of the naïve and sham controls." (PMID 29896429, 2018). "A steep rise of [K+]o immediately after the onset of terminal ischemia/anoxia was faster and reached its maximum in GFAP/EGFP/α-Syn−/− mice in about 3 min after cardiac arrest." (PMID 25426721, 2014). "In addition to NSE and S100B, several emerging neurobiomarkers—such as neurofilament light chain (NfL), Tau, and glial fibrillary acidic protein (GFAP)—have shown promise for outcome prediction after cardiac arrest." (PMID 40759951, 2025). "Elevated GFAP may also be seen in healthy individuals with developing Alzheimer's pathology, but levels are lower than those seen after cardiac arrest." (PMID 38594704, 2024). "At ICU admission, 12 h and 48 h post-cardiac arrest, GFAP predicted neurological outcome after OHCA with AUC (95% CI) 0.76 (0.70–0.82), 0.86 (0.81–0.90) and 0.91 (0.87–0.96), and after IHCA with AUC (95% CI) 0.77 (0.66–0.87), 0.83 (0.74–0.92) and 0.83 (0.71–0.95)." (PMID 38594704, 2024). "The predictive ability of GFAP may be sufficiently high for clinical use at 12 h after cardiac arrest." (PMID 38594704, 2024). "A previous study determined the neoepitope that is generated by caspase-6-mediated cleavage of GFAP (GFAP-C6) and assessed the ability of GFAP-C6 to reflect pathological processes in patients suffering from cardiac arrest (CA) and subsequent global cerebral ischemia." (PMID 39001884, 2024). "We did not detect any significant reduction in the glial fibrillary acidic protein immunostained areas with indoleamine 2,3-dioxygenase deficiency within the white matter tract and the caudoputamen after cardiac arrest." (PMID 37487175, 2023). "In this cohort study of 120 children who were resuscitated after cardiac arrest, blood concentrations of 4 brain injury biomarkers (glial fibrillary acidic protein, ubiquitin carboxyl-terminal esterase L1, neurofilament light, and tau) were associated with unfavorable outcomes at 1 year." (PMID 36074465, 2022). "Interestingly, GFAP levels peaked at 24 h after cardiac arrest before decreasing from day to day after brain hypoxia, while long-term data are missing." (PMID 36142218, 2022). "Three days after cardiac arrest and resuscitation, the percentage of pixels with GFAP+ immunoreactivity, determined by image segmentation and calculated against the total number of pixels in the region of interest, increased nearly 3-fold compared to the naïve mice." (PMID 29896429, 2018).
cardiac arrest (continued). "Additionally, GFAP displayed excellent performance already 12 h post-cardiac arrest, regardless of the location (OHCA or IHCA) or cause of the arrest (cardiac vs non-cardiac), but was not a reliable predictor of outcome at ICU admission." (PMID 38594704, 2024). "Novel biomarkers, including neurofilament light (NFL), glial fibrillary acidic protein (GFAP), total-tau, and phosphorylated tau, have shown promising prognostic value after cardiac arrest." (PMID 38594704, 2024). "The area under the curves of the novel serum biomarkers were highest at 72 h after cardiac arrest (CA) (0.906 for Tau, 0.946 for NFL, 0.875 for GFAP, and 0.935 for UCH-L1)." (PMID 36927495, 2023). "As expected, extensive Iba-1-positive, GFAP-positive, and CD68-positive cells appeared in the hippocampal CA1 region in the post-cardiac arrest rats treated with vehicle solution compared to the sham controls." (PMID 32703306, 2020). "Microglia and astrocytes were dramatically activated in the post-cardiac arrest hippocampal CA1 region, as evidenced by increased immunoreactivities of Iba-1 for microglia and GFAP for astrocytes." (PMID 32703306, 2020). "However, our studies on GFAP and NFL at 12 h after cardiac arrest were performed in the same patients and require validation." (PMID 38594704, 2024). "The purpose was to evaluate glial fibrillary acidic protein (GFAP) and total-tau in plasma as predictors of poor neurological outcome after out-of-hospital (OHCA) and in-hospital cardiac arrest (IHCA), including comparisons with neurofilament light (NFL) and neuron-specific enolase (NSE)." (PMID 38594704, 2024). "Glial fibrillary acidic protein (GFAP), ubiquitin carboxyl-terminal esterase L1 (UCH-L1), neurofilament light (NfL), and tau concentrations were measured in blood samples from days 1 to 3 after cardiac arrest." (PMID 36074465, 2022). "However, Ac-YVAD-cmk treatment significantly reduced Iba-1-positive, GFAP-positive, and CD68-positive cells in the hippocampal CA1 region of post-cardiac arrest rats." (PMID 32703306, 2020). "Because S100β and GFAP were not selected for analysis, glial disintegration by cardiac arrest was not assessed in this study." (PMID 28950909, 2017). "Importantly, in the hypothalamus cardiac arrest did not activate structural markers of neuroinflammation in microglia (CD11b) or astroglia (GFAP)." (PMID 28957432, 2017). "On the contrary, in a cohort of adult patients with post-cardiac arrest electrographic status epilepticus, even though GFAP levels were significantly increased at 72 h, electrographic status epilepticus did not appear as an independent predictor of serum GFAP levels (while it was for NfL)." (PMID 37569895, 2023).
meningitis (21 papers, 2006 to 2025). A disorder characterized by acute inflammation of the meninges of the brain and/or spinal cord. "Here, the levels of ALOX5, S100B, DEFA1, and GFAP in the CSF of patients with meningitis caused by different infectious agents were compared to those of healthy controls." (PMID 38115295, 2023). "Anti-GFAP antibody testing should be routinely performed in patients with suspected tuberculosis meningitis to avoid misdiagnosis." (PMID 37338614, 2023). "ROC curve analysis was performed to differentiate the variation in ALOX5, S100B, DEFA1, and GFAP between groups to distinguish meningitis patients from healthy individuals and from different types of meningitis." (PMID 38115295, 2023). "According to the heat map, ALOX5, S100B, DEFA1, and GFAP levels were partially increased in the meningitis group versus controls." (PMID 38115295, 2023). "Comparison of CSF levels of ALOX5, S100B, DEFA1, GFAP in the groups with infectious meningitis and in the healthy control groups." (PMID 38115295, 2023). "The levels of reactive gliosis, marked by the GFAP-positive area, were significantly elevated after meningitis induction compared with those in normal controls." (PMID 35888118, 2022). "The astroglial cell responses, as determined by anti-GFAP immunohistochemistry and Gfap mRNA quantifications, revealed strong GFAP expression induction in meningitis mice, which was robustly ameliorated by Ac2-26 treatment." (PMID 33121515, 2020). "Because TSPO overexpression was also detected in reactive astrocytes, we determined GFAP protein expression, which was increased in both the 24-h and 10-day meningitis groups." (PMID 31901235, 2020). "In the meningitis group, we observed increased expression of GFAP (P < 0.05), a marker of astrocytes, 24 h after infection, with no significant change in IBA-1, Oligo, and NeuN levels in the PFC." (PMID 31901235, 2020). "To understand the glial contribution after meningitis, we evaluated the levels of microglial (IBA-1, CD 11B), astrocyte (GFAP), oligodendrocyte (Oligo), and neuronal (NeuN) markers 24 h and 10 days after experimental meningitis induction." (PMID 31901235, 2020). "In line with our results on the mRNA level, the density of GFAP-expressing cells increased in meningitis-induced mice, and this increase was ameliorated by Ac2-26 (p < 0.01; two-way ANOVA followed by Bonferroni test)." (PMID 33121515, 2020). "Positive MARCO staining and MARCO/GFAP co-localization were also shown after 12, 22, 39 h of infection with SP, albeit weaker than in meningitis by NM." (PMID 21299846, 2011). "Some anti-GFAP staining was detected in normal conditions but the immunostaining was highly increased in meningitis cases." (PMID 16948860, 2006). "This study showed that the parameters ALOX5, S100B, DEFA1, and GFAP could discriminate between meningitis patients and healthy controls, although with varying degrees of reliability." (PMID 38115295, 2023). "In addition, CSF DEFA1 and GFAP levels in the heat map were also successful in discriminating between the control and the meningitis groups." (PMID 38115295, 2023). "To determine whether meningitis caused by DE205B infection caused neurological damage, we detected for glial fibrillary acidic protein (GFAP), a marker of nerve damage, in brain tissue." (PMID 36143390, 2022). "However, in the hippocampus, we found a significant increase in the expression of microglial markers IBA-1 (P < 0.05) and CD 11B (P < 0.05) and astrocyte marker GFAP (P < 0.05) in the meningitis group after 24 h of infection." (PMID 31901235, 2020). "Indeed, a transcript indicative of activation of astrocytes (glial fibrillary acidic protein, or GFAP) was similarly upregulated in both the cortex and hippocampus of infant rats with meningitis." (PMID 28670576, 2017).